TSC1 (TSC complex subunit 1)
Diseases named in the same sentence as TSC1 in open-access papers (continued):
Sharing a sentence is not in itself a finding about the gene and the disease.
tuberous sclerosis (continued). "Additionally, in an in vivo study on a mouse model of tuberous sclerosis complex (TSC), the mutation in either TSC1 or TSC2 can disturb the function of NMDA receptors in the EI, which in turn can cause a shift from normal activity to ictal activity." (PMID 35002598, 2021). "Mutations in TSC1 and TSC2 genes cause tuberous sclerosis (TSC)." (PMID 34204582, 2021). "Tuberous sclerosis (TSC) is a systemic, autosomal dominant genetic disorder caused by mutations of TSC1 or TSC2 genes that result in a constitutive activation of mTORC1 disturbing subsequently cellular differentiation, proliferation, and migration early in development." (PMID 32973442, 2020). "To distinguish causative links between mTORC1 and DKD from correlative variation, we studied the effect of increased mTORC1 activity in RPTCs by deleting Tsc1, an essential component of the tuberous sclerosis complex, which inhibits mTORC1 through phosphorylation of Rheb." (PMID 32726619, 2020). "All patients in our study underwent TSC1/2 gene test, four patients had mutations in pathogenic TSC1 or TSC2 genes, five patients met the clinical or genetic diagnostic criteria for tuberous sclerosis, accounting for 35.7% (5/14) of EAML patients diagnosed in our hospital during the same period." (PMID 33575217, 2020). "Transgenic mouse models of tuberous sclerosis such as Tsc2+/− and Tsc1+/− exhibit increased activity in the mTOR pathway, which is accompanied by deficits in long-term potentiation and spatial learning, which can be reversed by chronic treatment with a rapamycin, a mTOR pathway inhibitor." (PMID 30083288, 2018). "Tuberous sclerosis complex is closely related to the TSC1/TSC2 genes." (PMID 30185235, 2018). "Tuberous sclerosis (TSC) is a neurodevelopmental disorder that is caused by autosomal dominant mutations in the TSC1 or TSC2 tumor suppressor genes, which function as negative regulators of the mTOR signaling cascade." (PMID 26483618, 2015). "PEComas may be associated with the tuberous sclerosis complex (TSC), an autosomal dominant neurocutaneous disorder caused by genetic alterations of the TSC1 (9q34) or TSC2 (16p13.3) genes, and characterized by mental retardation, seizures and multiple tumors in different sites." (PMID 24575738, 2014). "It inactivates the tuberous sclerosis TSC1/2 inhibitors of mTOR." (PMID 23389114, 2013). "Rheb may be indirectly activated by ERK, through inhibition of the Rheb suppressor TSC1/2 (tuberous sclerosis complex), which stimulates the hydrolysis of GTP-bound Rheb to GDP-bound Rheb." (PMID 24391850, 2013). "Mutations to the TSC1 and TSC2 genes cause the disease tuberous sclerosis complex." (PMID 23006675, 2012). "Tuberous sclerosis genes, hamartin (TSC1) and tuberin (TSC2) are involved in this pathway." (PMID 21283628, 2011). "A TSC1 variant was detected in a patient without cutaneous stigmata of tuberous sclerosis complex." (PMID 41153369, 2025). "Although it frequently appears in tuberous sclerosis—a condition more often associated with a mutation in the TSC2 tumor suppressor gene rather than TSC1, which aberrantly activates the mTOR pathway—LAM is commonly diagnosed in its sporadic form (S-LAM), primarily affecting the lungs." (PMID 39858105, 2025). "TSC1 is potentially associated with common epilepsy without tuberous sclerosis." (PMID 40217423, 2024). "Second, the number of cases with TSC1 variants without tuberous sclerosis is limited." (PMID 40217423, 2024). "For example, in tuberous sclerosis complex (TSC) genetic disorder, EVs from TSC-1 null cells transform the phenotype of neighboring wild-type cells to mimic the diseased cell." (PMID 37181750, 2023). "Tuberous sclerosis complex is caused by pathogenic germline mutations of either the TSC1 or TSC2 gene, but somatic mutations were identified in both genes, and the combined effects of TSC1 and TSC2 mutations have been unknown." (PMID 36732866, 2023).
tuberous sclerosis (continued). "Tuberous sclerosis (TSC) and its domains (Tsc1 and Tsc2) are responsible for autosomal-dominating disorders, including epilepsy, skin, retina, heart, kidney, and the central nervous system." (PMID 36362447, 2022). "The aim of this study was to assess the potential implication of microRNA on tuberous sclerosis (TSC) pathogenesis by performing microRNA profiling on cell lines silencing TSC1 or TSC2 genes using qPCR panels, before and after incubation with rapamycin." (PMID 36430972, 2022). "Tuberous sclerosis (TSC) is a hereditary systemic disease characterized by systemic hamartoma, with TSC1 and TSC2 identified as the genes responsible for this condition." (PMID 36362756, 2022). "Hyperactivation of mTORC1, through loss-of-function mutations in the genes TSC1 or TSC2, causes the multisystem disorder tuberous sclerosis complex (TSC)." (PMID 34381067, 2021). "Tuberous sclerosis complex (TSC) is characterized by a mutation in either the TSC1 or TSC2 genes; approximately 50% of patients with TSC have ASD." (PMID 33396736, 2020). "However, since TSC1/2 activity does not always correlate with clinical manifestations as evident in some cases of tuberous sclerosis, the intriguing possibility is raised that phenotypes observed in Tsc1/2 knockout mice cannot be attributable solely to mTORC1 hyperactivation." (PMID 30808980, 2019). "Moreover, loss-of-function mutations of TSC1/TSC2 genes that lead to the inactivation of TSC—a negative regulator of mTOR—are present in patients with tuberous sclerosis, a population particularly predisposed to the development of RCC." (PMID 30510618, 2018). "Thus, TSC1-mTOR signalling acts as an important checkpoint for maintaining oligodendrocyte homoeostasis, pointing to a previously uncharacterized ER stress mechanism that contributes to hypomyelination in tuberous sclerosis." (PMID 27416896, 2016). "The pathological basis of LAM is associated with Tuberous Sclerosis Complex (TSC), a multi-system disorder marked by low-grade tumors in the brain, kidneys, heart, eyes, lung and skin, arising from inherited or spontaneous germ-line mutations in either of the TSC1 or TSC2 genes." (PMID 25505789, 2014). "Mutations of tumor suppressor genes tuberous sclerosis complex 1 (TSC1) and TSC2 are linked to the pathobiology of hamartoma syndrome Tuberous Sclerosis (TSC) and pulmonary lymphangioleiomyomatosis (LAM)." (PMID 25360538, 2014). "Neurofibromin 1 (NF1), tuberous sclerosis complex (TSC1/TSC2), and phosphatase and tensin homolog (PTEN) are genes associated with neurological diseases with common autistic symptoms including neurofibromatosis, tuberous sclerosis, and Cowden/Lhermitte-Duclos syndrome." (PMID 23935565, 2013). "LAM may present sporadically (S-LAM) or in association with tuberous sclerosis complex (TSC-LAM), which is caused by mutations in the TSC1 and TSC2 tumor suppressor genes." (PMID 40641534, 2025). "It is a rare, chronic progressive disease primarily affecting reproductive-age women when tuberous sclerosis complex 1/2 (TSC1/2) genes mutation occurs in germline or somatic cells, which separately refers to tuberous sclerosis complex associated LAM (TSC-LAM) or sporadic LAM (S-LAM)." (PMID 38267973, 2024). "The TSC1 and TSC2 genes are connected to multiple syndromes from Tuberous Sclerosis Complex (TSC) to autism spectrum disorder (ASD), with uncertainty if genetic variants cause all or subsets of phenotypes based on the location and type of change." (PMID 33071758, 2020). "Mutations in TSC1 and TSC2 are known to cause Tuberous Sclerosis (TSC)." (PMID 31245336, 2019). "Just as regional TSC1 and TSC2 gene expression patterns contribute to the development of tumors and hamartomas elsewhere in the body, we hypothesized that regional TSC1/TSC2 expression in the brain may influence neuroanatomic and cognitive changes associated with tuberous sclerosis." (PMID 30190613, 2018).
tuberous sclerosis (continued). "Mutations in the TSC1 and TSC2 genes cause tuberous sclerosis complex (TSC), a genetic disease often associated with epilepsy, intellectual disability, and autism, and characterized by the presence of anatomical malformations in the brain as well as tumors in other organs." (PMID 26693177, 2015). "Since the finding that the tuberous sclerosis genes TSC1 and TSC2 are suppressors of the mTOR signaling pathway, mTOR inhibitors have been used as a treatment approach in tuberous sclerosis." (PMID 26248290, 2015). "Both TSC1 and TSC2 are tumor suppressors and are mutated in tuberous sclerosis (TSC)." (PMID 28548055, 2013). "TSC1 and TSC2 constitute the tuberous sclerosis complex and hamartin and tuberin constitute their respective protein products." (PMID 16412252, 2006). "Nevertheless, further research is required to elucidate how different post-translational modifications affect TSC1 and TSC2 protein regulation, which could greatly influence the development of tuberous sclerosis complex treatments." (PMID 39901197, 2025). "As an example, Tsc1 and Tsc2 (Tuberous sclerosis complex) knockouts do not lead to the development of seizures in mice, unlike tuberous sclerosis cases in humans." (PMID 36428502, 2022). "The TSC1 gene on chromosome 9q34 was firstdiscovered in 1997 (van Slegtenhorst etal., 1997), though the TSC2 gene onchromosome 16p13.3 was discovered in 1993 (EuropeanChromosome 16 Tuberous Sclerosis Consortium, 1993)." (PMID 35638823, 2022). "In 25 patients (13.6%), variations were identified in TSC1, whereas in 85 patients (46.2%), variations were observed in TSC2 (TSC1:TSC2 ratio 1:3.4), and five patients (2.7%) suffered from a polycystic kidney disease with tuberous sclerosis (PKDTS), which is a contiguous gene deletion syndrome." (PMID 34154622, 2021). "In fact, human patients with N525S in TSC2 display severe symptoms of tuberous sclerosis without affecting TSC1/2 complex formation or GAP activity toward Rheb, whereas G1556S mutation impairs GAP activity with mild symptoms." (PMID 30808980, 2019). "However, given the absence of clinical evidence for tuberous sclerosis and NGS revealing no mutations in TSC1 or TSC2, the PDs for these two cases were glioma, NEC." (PMID 37998600, 2023). "Concurrent TSC1 testing did not detect any PV/LPV or VUS, making the tuberous sclerosis testing scenario one of the locus homogeneity scenarios." (PMID 40702147, 2025). "TSC1 and TSC2 are a part of a complex in mice that, when not present such as in tuberous sclerosis, lead to uncontrolled mTORC1 activation." (PMID 32341806, 2020). "The prevailing theory suggests the involvement of TSC1/TSC2 genes and sex hormones in its pathogenesis, yet the emergence of cases in females and those without tuberous sclerosis contradicts this hypothesis." (PMID 38989358, 2024). "Moreover, polymorphic and non-pathogenicvariants in the TSC1 and TSC2 genes can act asphenotype modifiers in tuberous sclerosis, and they need to be further explored." (PMID 28222202, 2017).
epilepsy (97 papers, 2010 to 2026). A brain disorder characterized by episodes of abnormally increased neuronal discharge resulting in transient episodes of sensory or motor neurological dysfunction, or psychic dysfunction. "Children with TSC2 variants tend to develop epilepsy significantly earlier compared to those with TSC1 variants." (PMID 40745330, 2025). "TSC is a rare genetic disorder caused heterozygous mutations in either the Tsc1 or Tsc2 genes, typically leading to serious neurologic comorbidities, such as severe epilepsy." (PMID 39010669, 2024). "Tuberous sclerosis complex is a rare form of ASD that is often accompanied by epilepsy and cognitive deficits, caused by mutations in either of the Tuberous sclerosis complex 1 or 2 (Tsc1/2) gene." (PMID 38716113, 2024). "Of the patients in the China Epilepsy Gene 1.0 project, 22 patients carried TSC1 variants and were diagnosed with TSC." (PMID 40217423, 2024). "In this study, two patients with TSC1 variants were seizure-free after administration with ASMs, suggesting the important role of ASMs in the treatment of patients with epilepsy caused by TSC1 variants." (PMID 40217423, 2024). "Of note, epilepsy onset occurred later in life in our patients with TSC1 variants than patients with TSC2 variants (3.2 years vs. 0.6 years, respectively)." (PMID 37946245, 2023). "Tuberous sclerosis complex (TSC) is a multisystem genetic disorder due to autosomal dominant mutations of either the TSC1 or TSC2 genes which are among the most common genetic causes of epilepsy." (PMID 35343625, 2022). "Mutations in regulators of mTORC1, such as Tsc1 and Tsc2, lead to neurodevelopmental disorders associated with autism, intellectual disabilities and epilepsy." (PMID 34135323, 2021). "Regulators of mTORC1, such as Tsc1, are involved in neurodevelopmental disorders associated with autism, intellectual disabilities and epilepsy." (PMID 34135323, 2021). "Tuberous sclerosis complex (TSC) is a congenital disorder characterized by cortical malformations and concomitant epilepsy caused by loss‐of‐function mutations in the mTOR suppressors TSC1 or TSC2." (PMID 33786950, 2021). "TSC1 mutations were associated with less severe epilepsy phenotypes and more individuals with normal IQ." (PMID 34566842, 2021). "A very recent study reported mutation analyses, clinical features, and tissue proteomic profiles of three patients with epilepsy caused by truncating TSC1 mutations." (PMID 33488359, 2020). "For instance, TSC2 mutations were more common than TSC1 mutations and the prevalence of certain disease features such as cortical tubers, subependymal nodules and epilepsy were similar to previous reports." (PMID 28057044, 2017). "Among these are RACK1 (involved in neuronal excitation), TSC1 (control of axon formation, epilepsy), APP (seizure susceptibility), HSPBAP1 (upregulated in epilepsy patients) and p190 RhoGAPs (involved in neuronal differentiation and process outgrowth)." (PMID 22016787, 2011). "Moreover, they are more likely to experience infantile spasms and have poorer epilepsy control and neurodevelopmental outcomes than their counterparts with TSC1 variants." (PMID 40745330, 2025). "TSC2 mutations were more prevalent than TSC1 mutations in people with TSC-associated epilepsy." (PMID 41291828, 2025). "Likewise, the surgical outcomes of epilepsy are less responsive in those with TSC2 compared with TSC1 variants." (PMID 38540392, 2024). "In this study, we identified four TSC1 variants in four patients with epilepsy." (PMID 40217423, 2024). "The correlation between the clinical characteristic of the patient, including multiple hamartomas in both kidneys, ungual fibromas, and a suspected history of epilepsy, with the identified TSC1 gene variant strongly supports the pathogenicity of the variant in causing the observed phenotype." (PMID 39432612, 2024).
epilepsy (continued). "The correlation between the clinical data of the patient, including atypical vitiligo‐like skin lesions, ungual fibromas, and a suspected history of epilepsy, with the identified TSC1 gene variant strongly supports the pathogenicity of the variant in causing the observed phenotype." (PMID 38439608, 2024). "This study aims to investigate the association between TSC1 variants and common epilepsy." (PMID 40217423, 2024). "In this way, inactivation of the Tsc1 gene in astrocytes causes defects in astrocytic gap junctions and potassium clearance, which may contribute to the development of epilepsy in this strain of mice." (PMID 35054848, 2022). "Thus, specific Tsc1 disruption in astrocytes is sufficient to cause neuronal abnormalities and epilepsy." (PMID 34298906, 2021). "Besides factors related to epilepsy and epilepsy treatment, several other factors have also been correlated with cognitive functioning, including if the patient had a mutation in TSC1 or TSC2." (PMID 27878438, 2017). "Despite the different effects at the synaptic level, our data suggest that loss of Pten or Tsc1 may both lead to an increase in the ratio of excitation to inhibition at the network level, an effect that has been proposed to underlie both epilepsy and autism." (PMID 24574959, 2014). "The loss of Tsc1 in RORγt-expressing cells not only caused neuronal defects but also induced astrogliosis, indicating that epilepsy and death caused by the inactivation of Tsc1 in RORγt-expressing cells might be due to both the abnormal discharge of neurons and activated astrocytes." (PMID 33957945, 2021). "Although seizures could have an additive effect, increasing the likelihood of developing autistic-like behaviours, the role of epilepsy has been widely discussed in the last years, and the TSC1/2 gene mutation is now considered to be sufficient to lead to social deficits." (PMID 31163675, 2019). "Because the levels of multiple immunoproteasome subunits were increased in the Tsc1-cko mouse brain, future studies should also investigate the potential involvement of the immunoproteasome in various brain disorders, such as autism and epilepsy, caused by mTORC1 hyperactivation." (PMID 29950673, 2018). "The authors reported that the phenotype observed, by inactivating Tsc1 at 2 weeks of age, was much less severe compared to prenatal Tsc1 inactivation, indicating that the severity of neural cell abnormalities and the resulting epilepsy are dependent on the developmental timing of TSC1 loss." (PMID 29772672, 2018). "One study specifically reported the proportions of patients with epilepsy as being 86% for patients with TSC2 mutations, but only 35% for patients with TSC1 mutations." (PMID 41291828, 2025). "Disruption of mTOR signaling due to variants in its repressors such as TSC1, TSC2, DEPDC5, PTEN or in its activators such as RHEB, and MTOR lead to a set of disorders characterized by early onset and often drug-resistant epilepsies called mTORopathies." (PMID 40792287, 2025). "Background and Aims: Tuberous sclerosis complex (TSC) is a neurodevelopmental disorder caused by mutations in TSC1 or TSC2, associated with widespread network dysfunction and drug‐resistant epilepsy." (PMID 40542572, 2025). "The diminished regulatory function of TSC1 results in the activation of the mTOR pathway, which subsequently leads to tumorigenesis and epilepsy." (PMID 40217423, 2024). "The cohort from another epilepsy center (n = 23) has a TSC1:TSC2 ratio of 1:1.4 (9:13) and more familial cases." (PMID 39596632, 2024). "In epilepsies caused by alterations in mTOR pathway genes, such as DEPDC5, TSC1, or TSC2, the drug rapamycin can be used to manage symptoms as it inhibits mTOR pathway." (PMID 37834053, 2023).